SPOP (speckle type BTB/POZ protein)
Diseases named in the same sentence as SPOP in open-access papers (continued):
Sharing a sentence is not in itself a finding about the gene and the disease.
tumor (continued). "Moreover, the patient-derived SPOP mutation Q360* impaired its nuclear localization, leading to NANOG accumulation in the nucleus, thereby driving tumor growth and metastasis." (PMID 40521202, 2025). "In RCC, the aberrantly overexpressed SPOP is positively correlated with tumor metastasis." (PMID 41122967, 2025). "Importantly, recent research has confirmed that SPOP functions as a tumor suppressor in hepatoblastoma (HB) development via the PI3K/Akt pathway, with its anti-cancer activity impaired by the S119N mutation." (PMID 40521202, 2025). "Moreover, in a B16-OVA tumor model, SPOP inhibition similarly enhances CD4+ CAR.CD19-T cell tumor infiltration, resulting in improved tumor control." (PMID 41148213, 2025). "Similarly, Atezolizumab mitigated tumor weight differences between the SPOP + LMNB2 + sh-NC and SPOP-M35L + LMNB2 + sh-NC groups, suggesting that SPOP mutations in HCC promote immune evasion partly through LMNB2." (PMID 40483310, 2025). "Although multiple downstream effectors of SPOP have been identified, little is known about the upstream regulatory mechanisms that may influence the tumor suppressive function of SPOP in HCC." (PMID 38340178, 2024). "Therefore, SPOP plays oncogenic or anti-tumor roles depending on its substrates in distinct cancers." (PMID 38409107, 2024). "Besides, the expression level of SPOP and total protein of SPOP in the tumor tissues of PAAD is higher than the corresponding control tissues." (PMID 39074086, 2024). "We next to evaluate the correlation of SPOP levels with tumor-infiltrating immune cells (TICs)." (PMID 39074086, 2024). "In this study, we identify the tumor suppressor IRF2BP2 as a novel substrate of SPOP." (PMID 38409107, 2024). "We hypothesized that there might be some potential relationships between SPOP and tumor-infiltrating immune cells (TICs)." (PMID 39074086, 2024). "Notably, ELK3 protein levels were markedly elevated in the SPOP-mutant tumor tissue compared to the tissue surrounding the normal area." (PMID 38632244, 2024). "Taken together, our studies show that the M35L mutation reprograms SPOP from a tumor suppressor to a tumor promotor without affecting its protein level." (PMID 38409107, 2024). "Therefore, CDK4/6 inhibitors can enhance the ubiquitination function of SPOP, promoting anti-tumor immune responses." (PMID 39315102, 2024). "In this study, we find the tumor suppressor IRF2BP2 as a novel substrate of SPOP." (PMID 38409107, 2024). "Since mutants of the SBC-associated BCLAF1 display deficiencies in BCLAF1-SPOP interactions and BCLAF1's regulation of the SPOP-PD-L1 axis, we investigated whether BCLAF1-mSBC influences BCLAF1's function in HCC tumor immunity." (PMID 38340178, 2024). "Since most of the reported substrates are oncoproteins, SPOP is considered as a tumor suppressor." (PMID 38409107, 2024). "In addition, many proteins identified as substrates of SPOP are involved in cancer development and progression, classifying SPOP as a tumor suppressor." (PMID 39540935, 2024). "Notably, Speckle-type POZ protein (SPOP) serves as a tumor suppressor through its function as a substrate receptor for Cullin 3 (CUL3)-based ubiquitin ligases and mediates ubiquitination and degradation of PD-L1." (PMID 38340178, 2024). "Knockdown of SPOP in PC cells enhances invasive ability, pointing to its tumor-suppressive role." (PMID 38409107, 2024). "Meanwhile, SPOP also played a crucial role in the tumor microenvironment (TME)." (PMID 39074086, 2024). "SPOP can impede the stemness of several cancers as a tumor suppressor." (PMID 36769824, 2023). "Notably, a previous study has suggested SPOP as a tumor suppressor in glioma to inhibit cell viability, migration, and invasion in vitro." (PMID 37382594, 2023).
tumor (continued). "In conclusion, the present study suggested that miR-873-5p may act as a tumor suppressor in GBM progression by downregulating the HMOX1/HIF1α/SPOP signaling axis." (PMID 37382594, 2023). "Furthermore, expression of miR-873-5p was increased, but that of HMOX1, HIF1α, and SPOP was reduced in the tumor tissue of mice treated with miR-873-5p agomir + oe-NC." (PMID 37382594, 2023). "The downstream signaling pathways and the corresponding molecular mechanisms of SPOP manifest the potential of its tumor-promoting effect in HCC, and thus SPOP may serve as a new opinion for underlying tumor-promoting effect in HCC." (PMID 37941785, 2023). "Notably, Kelch ECH-associated protein 1 (Keap1) and the speckle-type POZ protein (SPOP) are recognized as cancer-associated adaptors of CUL3, exerting pivotal roles in tumor progression." (PMID 37906282, 2023). "In conclusion, SPOP may potentially exhibit tumor-promoting effects, necessitating further investigations to unveil its molecular mechanisms comprehensively." (PMID 37941785, 2023). "We also confirmed that ASCT2 or SPOP were indeed knocked down in respective tumor tissues." (PMID 35641493, 2022). "Similarly, SPOP can have a tumor-suppressing role if the majority of substrates that bind to SPOP play the tumor promoting role." (PMID 36474188, 2022). "The inversed protein levels were found between ASCT2 and SPOP in both non-tumor and tumor tissues." (PMID 35641493, 2022). "We performed a comprehensive pathological review of over 300 RPs from a prospectively collected multi-institutional cohort and mapped and graded each tumor focus based on H&E examination and molecular classifiers (ERG rearrangement, SPINK1 overexpression, PTEN deletion, and SPOP mutation)." (PMID 35050902, 2022). "As a result, SPOP knockdown markedly reduced F18-FDG uptake into the tumours in vivo." (PMID 36042498, 2022). "The dysregulation of SPOP-mediated proteolysis is associated with the development and progression of different cancers since abnormalities in SPOP function dysregulate cellular signaling pathways by targeting oncoproteins or tumor suppressors in a tumor-specific manner." (PMID 36360288, 2022). "The inhibitory role of SPOP was confirmed by an earlier study that showed that downregulation of SPOP expression in cancers might inhibit its functions as a tumour suppressor gene and promote cancer development." (PMID 36474188, 2022). "PCa-associated missense mutations in the MATH domain of SPOP disrupt substrate binding and ubiquitination, leading to upregulated oncogenic substrate levels and increased PCa cell proliferation and invasion, indicating the tumor-suppressive role of SPOP in PCa." (PMID 35194188, 2022). "We did not observe differences in SPOP mutation or CHD1 loss frequency by tumor BRCA2 status, although these genes have been implicated in impaired HR repair." (PMID 35715489, 2022). "SPOP is an E3 ubiquitin ligase adapter that can serve as a tumor suppressor." (PMID 35461336, 2022). "Given that previous studies showed that SPOP could restrict tumor autophagy via p62, we thus questioned whether SPOP could depend on CHAF1A/TFEB to regulate autophagy." (PMID 35773729, 2022). "We then extended this observation to the in vivo xenograft tumor model derived from MDA-MB-231 cells after shRNA-based knockdown of ASCT2 or SPOP or both and found that consistent with cell culture model, ASCT2 knockdown inhibited, whereas SPOP knockdown promoted tumor growth." (PMID 35641493, 2022). "However, some studies identified mutant SPOP in 6–15% of PCa and it can alleviate the tumor suppressive effect." (PMID 36009418, 2022).
tumor (continued). "By re-analyzing ChIP-Seq data, we could determine that most differentially bound regions between both tumor types are characterized by increased AR-binding in SPOP-mutant tumors." (PMID 33531470, 2021). "Notably, mutant SPOP can dimerize with the wild type (WT) counterpart to repress WT SPOP tumor suppressive functions." (PMID 34353330, 2021). "As such, SPOP plays an unique role in maintaining a steady-state level of AR signaling in prostate epithelial cells and regulating oncogenic transcription, DNA damage repair, and tumor cell migration." (PMID 34795264, 2021). "SPOP is an adaptor protein of Cullin 3-based E3 ubiquitin complexes, has been shown to participate in diverse cellular processes and plays tumor suppressive roles in PrCa, suggesting that HnRNPK may be a substrate of SPOP." (PMID 34857003, 2021). "This may be due to mutations in cell division and growth-regulating genes such as ATK1 and SPOP, which increases the number of divisions in the tumour and thereby shortens tumour telomeres." (PMID 34824250, 2021). "Remarkably, ERG-fused human tumor tissues also displayed the highest SPOP mRNAs levels." (PMID 33531470, 2021). "Although multiple downstream effectors of SPOP have been defined, little is known about upstream regulatory mechanisms that may modulate the tumor suppressive function of SPOP." (PMID 34795264, 2021). "SPOP has been shown to participate in diverse cellular processes and plays tumor suppressive and oncogenic roles in PrCa by targeting different substrates for ubiqutination-mediated proteolysis, including AR, steroid receptor coactivator 3 (SRC-3), DEK, TRIM24, BRD4 and Nanog." (PMID 34857003, 2021). "Taken together, our data indicate that in different tissues or cellular compartmental conditions, SPOP might play different roles as tumor suppressor or oncogene in manipulating AKT kinase by degrading distinct substrates such as PDK1 or PTEN, respectively." (PMID 34353330, 2021). "Therefore, our work uncovers a previously unrecognized tumor suppressor role of SPOP in preventing DNA from over-replication and genome instability." (PMID 34599168, 2021). "ADAMTS9‐AS2 suppressed tumour spheroid formation of gastric cells through down‐regulating SPOP." (PMID 33345447, 2021). "In addition, the SPOP protein plays a role as a tumor suppressor that negatively regulates the stability of multiple other oncogenic substrates in PrCa, including AR, SRC-3, c-MYC, ERG, DEK, BRD4 and Trim24." (PMID 34857003, 2021). "Conversely, some studies have demonstrated that hypoxia leads to cytoplasmic accumulation of SPOP, which promotes tumorigenesis through the ubiquitination and degradation several tumor suppressors, such as PTEN, indicating that SPOP acts as a cancer-promoting factor in ccRCC5." (PMID 34021128, 2021). "In addition, we show that the bromodomain histone reader ZMYND11 is a SPOP substrate implicated downstream of SPOP in the opposing regulation of the ERG and AR pathway in the two tumor subtypes." (PMID 33531470, 2021). "uncovered that SPOP could promote ubiquitination-mediated programmed death ligand 1 (PD-L1) degradation, leading to decreased PD-L1 levels and increased numbers of tumour-infiltrating lymphocytes to regulate cancer immune surveillance." (PMID 34838022, 2021). "However, potential tumor suppressor functions of SPOP and CK1, as well as the predicted challenge of targeting SPOPCUL3, led us to evaluate for possible DUBs that would antagonize SPOPCUL3 function to stabilize EWS–FLI1." (PMID 34060252, 2021). "Importantly, non-SPOP recognized PDK1 also promoted tumor growth in mouse, coupled with increased AKT kinase activity." (PMID 34353330, 2021).
tumor (continued). "In agreement with our previous results, we found that ERG-fused cells (VCaP, LuCaP-23.1, −35) were more sensitive to SPOP-i than ERG-negative cells (22Rv1, LNCaP, PC3), while SPOP mutant cells (LuCaP-78, −147) were particularly insensitive in 3D culture models and in xenograft tumor models in vivo." (PMID 33531470, 2021). "SPOP overexpression in C4-2 cells resulted in reduced tumor growth as compared to C4-2 cells." (PMID 33158056, 2020). "It has been reported that E3 ubiquitin ligase SPOP acts as a tumor suppressor in PCa." (PMID 32364525, 2020). "Thus, phospho-resistant SPOP has higher tumor-suppressing potential as compared to wild type SPOP, presumably due to its resistance to AURKA-mediated degradation." (PMID 33158056, 2020). "Moreover, ADAMTS9‐AS2 acted as a tumour suppressor that inhibited the progression of GC through regulating the SPOP, and these findings indicated that SPOP and ADAMTS9‐AS2 can be potential targets for GC treatment." (PMID 32160650, 2020). "Interestingly, the ectopic expression of F133V SPOP increased the effect of radiation also in vivo, as shown by the statistically significant reduction in tumor growth upon irradiation compared to WT SPOP xenografts." (PMID 32512734, 2020). "In addition, experiments on subcutaneous tumor mouse model also confirmed the inhibitory effect of SPOP on liver and lung metastases in HCC." (PMID 31901237, 2020). "Hence, these studies recommend that SPOP serves as a tumor suppressor by regulating the degradation of its substrates in BC." (PMID 31901237, 2020). "In addition, knockdown of SPOP by shRNA promoted the proliferation and invasion of BC cells and elevated the cancer growth rate in a tumor xenograft mouse model, and these results were greatly influenced by upregulation of the SRC-3 oncoprotein." (PMID 31901237, 2020). "Importantly, the xenograft experiments showed that SPOP represses tumor growth rising from a PCa cell line and enhances tumor formation of a CCRC cell line." (PMID 30237511, 2019). "We have discovered two substrates for SPOP, one oncogene and one tumor-suppressor, which led us to investigate whether SPOP play opposite roles in PCa and CCRC." (PMID 30237511, 2019). "First, given that the biological functions of SPOP in cancers could vary, pooled analysis in single cancer type might be useful to specifically evaluate the prognostic role of SPOP in a certain type of tumor." (PMID 31577764, 2019). "Moreover, SPOP inactivation leads to compromised anti-tumor immunity by increasing PD-L1 protein stability in cancer cells." (PMID 31771591, 2019). "Speckle-type POZ protein (SPOP) has recently been reported as a prognostic tumor biomarker." (PMID 31577764, 2019). "The study of some of these patients with hormone-naïve and castration-resistant tumor samples established 17% CHD1 loss in tumor biopsies; CHD1 loss and/or SPOP mutations were associated with a higher response rate to Abiraterone and a longer time on Abiraterone." (PMID 31366128, 2019). "For this respect, SPOP plays an anti‐tumour role in Hh‐related NSCLC." (PMID 30407707, 2019). "Furthermore, the inhibition of the expression of the transcription factor C/EBPα can significantly reduce SPOP expression and ultimately affect cell migration, invasion and proliferation and tumor growth." (PMID 30607139, 2018). "Therefore, the expression of the SPOP gene in tumor cells involving a hypermethylated promoter is most likely repressed." (PMID 30607139, 2018). "We therefore hypothesized that SPOP exerts its tumor suppressor function partly through regulating the stability of HDAC6 oncoprotein." (PMID 28599312, 2017).
tumor (continued). "Here, integrated studies of transcriptomics and metabolomics as well as lipidomics were performed in matched PCa tumor (PCT) and adjacent non-tumor (ANT) tissues, followed by correlation analysis of SPOP mutations with altered metabolic pathways in SPOP-mutated PCa patients." (PMID 29262542, 2017). "Taken together, our data suggest SPOP might exert its tumor-suppressive roles both in nucleus and cytoplasm." (PMID 28448495, 2017). "Bioluminescence imaging results showed that SPOP significantly inhibited tumor growth." (PMID 28032859, 2016). "Moreover, Ki-67 staining of tumor xenografts confirmed that SPOP markedly decreased the fraction of Ki-67-positive tumor cells." (PMID 28032859, 2016). "We report herein that SPOP negatively regulates Hh/Gli2 signaling pathway mediated transcription through interfering Gli2 abundance in gastric cell lines, thus results in decreased tumor cell proliferation, invasion, migration and enhanced cell apoptosis." (PMID 25204354, 2014). "Therefore, SPOP is a tumor suppressor that is uniquely placed to deregulate, when mutated, the androgen signaling and three developmental pathways instrumental in prostate development and carcinogenesis." (PMID 25277175, 2014). "In addition, SPOP, a putative tumour suppressor involved in chromatin remodelling was found to be altered in 3 cases (14%)." (PMID 25233892, 2014). "Several studies indicate that SPOP regulates apoptosis in tumor cells." (PMID 25204354, 2014). "In addition, SPOP promotes tumor cell apoptosis through regulating the expression of Hh/Gli related apoptotic proteins." (PMID 25204354, 2014). "These in vitro results further confirmed that SPOP is a potential tumor suppressor in GC." (PMID 25204354, 2014). "In paclitaxel-resistant cells, DRAK1 protein is degraded by the SPOP through K48-linked polyubiquitination-mediated proteasomal degradation, leading to an increase in TRAF6 levels and subsequent TRAF6-mediated NF-κB activation, which promotes tumor progression." (PMID 40521202, 2025). "Furthermore, SPOP overexpression significantly suppressed tumor metastasis in a mouse model." (PMID 41082269, 2025). "Given the significance of SETD2 as a tumor suppressor and SPOP's role in regulating splicing, targeting this axis may offer new therapeutic opportunities in cancer treatment, particularly in cancers like RCC where both proteins are implicated in tumorigenesis and drug resistance." (PMID 40521202, 2025). "Therefore, wild-type SPOP is considered a tumor suppressor in PCa." (PMID 38104650, 2024). "In a word, downregulation of SPOP has been observed in cancer tissues compared with normal tissues, besides high expressed SPOP significantly correlated with a better prognosis of cancer, it’s may due to an uncovered inhibiting mechanism to promote tumor growth." (PMID 39074086, 2024). "Finally, the M35L mutation reprograms SPOP from a tumor inhibitor to an oncoprotein, without affecting SPOP abundance." (PMID 38409107, 2024). "Our aim was to analyze the protein expression of PTEN, SPOP, SLC45A3, ETV1, ERG and the “triple hit” (ERG overexpression, PTEN plus SLC45A3 loss) in unifocal (UF) and MF PCa, to evaluate their value as prognostic markers according to focality, and the role of tumor heterogeneity in MF disease." (PMID 38017230, 2024). "Thus, SPOP substrate targeting, its importance as a tumor-promoting or -repressing factor, and therapy sensitivity may be cancer- or cell-type specific." (PMID 37622993, 2023). "As some studies showed that the tumor-promoting and tumor-suppressing activities of SPOP may be owing to differential subcellular localization of SPOP or differential expression of SPOP substrates in the cell and cancer typespartially to alter its substrate availability." (PMID 36474188, 2022).